GDNF (glial cell derived neurotrophic factor)
Diseases named in the same sentence as GDNF in open-access papers (continued):
Sharing a sentence is not in itself a finding about the gene and the disease.
tumor (continued). "Cancer cells release neurotrophins like Nerve Growth Factor (NGF), Brain-Derived Neurotrophic Factor (BDNF), Glial Cell Line-Derived Neurotrophic Factor (GDNF), and artemin (ARTN), which bind to receptors on nerve cells, promoting neurite outgrowth toward the tumor." (PMID 40909268, 2025). "Transcriptomic profiling revealed that KPC organoids upregulated neurotrophic factors (NGF and glial cell line-derived neurotrophic factor (GDNF)) and axon guidance molecules (semaphorin 3A and Ephrin type A receptor 4 (EPHA 4)), implicating tumor-secreted signals in neural remodeling." (PMID 40243726, 2025). "Molecular profiling of tumor tissue or exosomes for neurotrophic factors (NGF, BDNF, GDNF), chemokines (CXCL12, CCL2), or neuronal transcription factors (POU4F1) may serve as predictive biomarkers of neural involvement." (PMID 41009819, 2025). "Experimental studies have shown that PNI in PDAC is an active process involving reciprocal tumour–nerve signalling via neurotrophic factors (e.g., NGF, GDNF, CXCL12), extracellular matrix remodelling, and Schwann cell activation, which together create a permissive niche for perineural invasion." (PMID 41227159, 2025). "Tumor innervation can be induced by cancer cells through the secretion of neurotrophins such as nerve growth factor (NGF), brain-derived neurotrophic factor (BDNF) and glial cell-derived neurotrophic factor (GDNF), amongst others." (PMID 40075699, 2025). "Of the few cytokine/chemokine/growth factor transcripts that differed in SC clusters between controls and Nf1 mutants before tumor formation predicted to uniquely affect neurons, GDNF was the only factor upregulated in SCPs and in nonmyelinating SCs." (PMID 38258905, 2024). "The combination of GDNF, CEA, and CA199 may improve the drawbacks of existing serum tumor markers and provide a reliable basis for pathological diagnosis by obtaining accurate results through a single blood test." (PMID 38699694, 2024). "GFRA1, interacting with glial cell-derived neurotrophic factor (GDNF), promotes tumor progression." (PMID 38962317, 2024). "Tumor-derived factors such as colony-stimulating factor 1 (CSF1; also known as M-CSF), granulocyte-macrophage colony-stimulating factor (GM-CSF), CC-chemokine ligand 2 (CCL2), CCL7 (or MCP-3), GDNF, IL-33, CXCL12 (SDF-1) and EGF are responsible for myeloid cell recruitment and promote tumor growth." (PMID 36140392, 2022). "The recruited macrophages assisted the polarization and migration of tumor cells through the GDNF/RET pathway without changing the direction of tumor migration." (PMID 34572820, 2021). "Moreover, although GDNF was present in the tumours, its expression was heterogenous, revealing that a combination of lack of apoptosis (low ARF) and increased RET kinase activity (GDNF) is playing a dual role in AIP+ tumour samples." (PMID 34588620, 2021). "These oncogenes, such as GDNF, STAT3, and SOX1, induce CAF activation and promote the overexpression of growth factors such as CXCL12 and Wnt/Notch for differentiating epithelial cells into tumor-initiating stem cells." (PMID 34513834, 2021). "A previous study demonstrated that circFOKX2 not only interacts with YBX1 and hnRNPK to elevate the expression of the oncogenes NUF2 and PDXK but also functions as a sponge for miR-942 to upregulate the expression of ANK1, GDNF, and PAX6, which contribute to tumor progression in PDAC." (PMID 34419070, 2021). "Recent evidence obtained in mice overexpressing GDNF in moderate levels (by 2 fold compared to wild-type littermates) revealed no enhancement of tumor formation during their life span." (PMID 32993133, 2020). "The fact that GDNF treatment did not affect clonogenic survival in vitro or tumor regrowth after radiation in vivo in different tested HNSCC cell lines was promising." (PMID 32084217, 2020). "GDNF is upregulated at the transcript level in LUSC, and is hypermethylated in tumor tissues." (PMID 32102656, 2020).
tumor (continued). "As GDNF is downregulated by MIR133B, it inhibits tumor migration and proliferation." (PMID 32211020, 2020). "We further investigated whether tumor progression in these tumors is driven by the expression of GFRA1 and RET receptors or GDNF which is regulated in response to the inflammatory microenvironment surrounding many epithelial cancers." (PMID 29617307, 2018). "In addition, significant increases were observed for GM-CSF (1.8-fold), Timp-1 (8.6-fold) Serpin E1, and tumor growth inducer HB-EGF (2.3-fold), TSP-1 (2.3-fold), GDNF (1.5-fold) in HT-29 TSs cultured with fibroblasts." (PMID 27391808, 2016). "However in vitro, NVP-AST487 was superior to letrozole in inhibiting the GDNF-induced motility and tumor spheroid growth of MCF7-AROM1 cells and required in combination with letrozole to inhibit GDNF-induced motility in BT474-AROM3 aromatase expressing cells." (PMID 27602955, 2016). "Multiple levels of treatment resistance that include cell intrinsic mechanisms, paracrine interactions between tumor and stroma, and the micro-architecture of the TME could be substantially affected by the induction of GDNF following genotoxic damage." (PMID 25575823, 2015). "We assessed whether patient ACC tumor specimens express RET, the cognate receptor for GDNF, using immunohistochemical staining." (PMID 22768171, 2012). "Also, BDNF, GDNF, NGF, and axon guidance molecules, such as CX3CL1, EphA2, CCL2, Slit, and so forth, are groups of neuroactive chemicals generated by the nerves involved in tumor–nerve interaction." (PMID 39346791, 2024). "Finally, iNPC-GDNF transplants in the spinal cord of athymic nude rats survive and produce GDNF for 9 months, with no signs of tumor formation or continual cell proliferation." (PMID 37084724, 2023). "GDNF-increased cancer cell aggressive behavior was markedly reduced in oral cancer when pharmacological inhibitors or neutralizing antibodies inhibited MMP-9 (matrix metalloprotein 9) and MMP-13, an enzyme family destroying the histological barrier of tumor cell invasion." (PMID 35582425, 2022). "However, comparing corresponding areas on consecutive sections stained for GH and for GDNF, we found more heterogeneous staining of GDNF in AIP+ tumours with negative populations interspersed with the stained cells in some samples." (PMID 34588620, 2021). "At the same time, tumor cells release chemoattractant proteins that recruit TAMs, such as CCL2, CSF-1, granulocyte–macrophage colony stimulating factor (GM-CSF), hepatocyte growth factor or scatter factor (HGF/SF), stroma-derived factor 1 (SDF-1), and glial cell-derived neurotrophic factor (GDNF)." (PMID 33766119, 2021). "As GDNF is highly expressed in NSCLC, we could hypothesize in RET inhibitors resistant cancer cells harboring MET amplification, a cross-talking between tumor microenvironment and TK receptors." (PMID 33806299, 2021). "The discrepancy may be due to the fact that TCGA measures gene expression of the tumor bulk, which is comprised of cancer and non-cancer cells in the tumor microenvironment; whereas the IHC data primarily focus on GDNF stromal protein staining." (PMID 32084217, 2020). "Likewise, GDNF treatment affected neither tumor growth in vitro nor response to radiation in xenografts in two HPV-positive and two HPV-negative HNSCC models." (PMID 32084217, 2020). "Understanding the upstream regulatory mechanisms that contribute to the secretion of GDNF and other DDSP components could provide strategies for suppressing the DDSP more broadly, and thereby limit the treatment counter-acting effects exerted by a damaged tumor microenvironment." (PMID 25575823, 2015). "The specific effects of the various factors secreted by them (such as GDNF, NGF, chemokines, etc.)in different tumor types and microenvironments have not been clearly identified." (PMID 41583906, 2026). "MSCs secrete VEGF, BDNF, NT‐3, NT‐4, GDNF, and SDF‐1α to promote neuroprotection and angiogenesis, with no endotoxin or tumor formation." (PMID 41427019, 2025).
tumor (continued). "We have previously studied the effect of GDNF in one HPV-negative HNSCC cell line, SCC22A, and found that the GDNF treatment did not modify SCC22A tumor growth or response to RT." (PMID 32084217, 2020). "For the HPV-negative cell lines, we had previously studied GDNF effect on SCC22A cells (HPV-negative with high GDNF/GFRα1 expression) and reported that high dose GDNF treatment did not affect SCC22A tumor growth or response to radiation." (PMID 32084217, 2020). "When analyzing each stage (IA, IB, IIB and IIIA) independently, the two most significant markers (GDNF and MTHFR) showed significantly higher DNA methylation levels in tumor vs. adjacent non-tumor in every stage, despite the modest number of cases." (PMID 18616821, 2008).
cancer (94 papers, 2008 to 2026). A tumor composed of atypical neoplastic, often pleomorphic cells that invade other tissues. "The reports suggest that there is still a possibility for GDNF to be linked to cancer cell aggressiveness." (PMID 32084217, 2020). "In an in vitro Matrigel coculture model of dorsal root ganglion and PCCs, nerve-secreted GDNF induced polarized neurotrophic migration of cancer cells (PNMCs) along the nerve axons, whereas deficiency of this mediator reduced the ability to attract cancer cells." (PMID 35582425, 2022). "Some (e.g., GDNF) have been found to be associated with cancer." (PMID 33601339, 2021). "GDNF and its receptors play a crucial role in various cancers by influencing cell proliferation, migration, and invasion." (PMID 40642294, 2025). "Collectively, these findings underscore the oncogenic potential of GDNF signaling across multiple cancer types." (PMID 40642294, 2025). "Evidence suggests that GDNF can promote the survival and spread of already occurring cancer cells in specific environments, such as the leptomeninges." (PMID 39968416, 2025). "GDNF promotes nerve sprouting and survival, particularly in densely innervated cancers such as head and neck and colorectal cancers." (PMID 41009819, 2025). "GDNF induces polarization and invadopodia formation in cancer cells, enabling matrix degradation through the production of matrix metalloproteinases, thereby accelerating cell invasion." (PMID 40427098, 2025). "Overexpression of Nodal in pancreatic cells upregulates the expression of NGF, BDNF and GDNF, enhancing the migratory and invasive abilities of cancer cells." (PMID 39119085, 2024). "Research in pancreatic cancer shows consistent overexpression of GDNF by both cancer and nerve cells, which acts through the Ret proto-oncogene (RET) receptor and GDNF family receptor (GFR) α1 to attract cancer cells to nerves." (PMID 39518134, 2024). "The SSC self-renewal gene Glial cell line-derived neurotrophic factor (GDNF) is associated with PAE disorders, and misexpression of GDNF produces malignant tumors in the testes that express germline markers." (PMID 39459551, 2024). "During tumorigenesis, cancer cells secrete colony-stimulating factor 1 (CSF-1) to recruit macrophages, which, in turn, release GDNF, promoting cancer migration as well as nerve invasion." (PMID 37610689, 2024). "GDNF and cyclophilin A upregulation contributed substantially to cancer cell survival and adaptation against immune responses and surveillance." (PMID 37833789, 2023). "Given our findings, one potential therapeutic option to treat GDNF-RET-EGR1 resistant BC cancer would be to inhibit both cyclin D1-CDK4/6 and ERα signaling." (PMID 36765275, 2023). "NE can also stimulate the production of IL-6 and activate macrophages in TME, which can promote cancer migration and nerve invasion by releasing GDNF." (PMID 36900158, 2023). "A further investigation into the epigenetics modifications and metabolic contribution to GDNF upregulation induced by testosterone will provide insight and help advance cancer therapy development." (PMID 37833789, 2023). "GDNF promotes cancer progression by binding to GDNF family receptors α1-3 and RET proto-oncogene (RET), which initiate the downstream activation of several signaling pathways, including RAS/ERK, MAPK, JNK, and PI3-K/Akt." (PMID 37566075, 2023). "A study of the effect of GDF-15 through glial cell-derived neurotrophic factor (GDNF) family receptor α-like protein (GFRAL) demonstrated that increased GDF-15 is related to the anorexia/cachexia observed in advanced cancer patients." (PMID 36008442, 2022). "Among these, glial cell line-derived neurotrophic factor (GDNF) promotes migration and recruitment to the perineural microenvironment of cancer cells." (PMID 35053395, 2022). "These macrophages are actively involved in mediating PNI via the secretion of the GDNF, which attracts and activates cancer cell migration toward nerves by binding with the GDNF receptors, RET/GFRα1." (PMID 35455973, 2022).
cancer (continued). "One of fb-PMT up-regulated cancer driver genes (RET) encodes a dependence receptor, which promotes cell survival following interactions with its ligand, GDNF." (PMID 36879662, 2022). "We found that blocking GDNF activity with a specific antibody completely inhibited NLGN1-induced in vitro cancer cell invasion of nerves." (PMID 35053395, 2022). "RET is activated through the glial cell line-derived neurotrophic factor (GDNF) family of ligands and has been reported to be activated in several cancer types." (PMID 36142729, 2022). "Similar changes have been reported in prostate cancer, as GFRα-1/RET binding of GDNF potentiates invasion and proliferation of cancer cells." (PMID 35223829, 2022). "GDNF has been shown to play a major role in the migration of cancer cells and PNI in several cancers." (PMID 34885121, 2021). "Several studies investigating head and neck SCC also highlight a role for GDNF in promoting cancer cell migration and PNI." (PMID 34885121, 2021). "With migration assays utilizing human oral SCC lines (SCC4 and HSC3), they also demonstrated that GDNF increased migratory activity of cancer cells through transwell assays in a dose-dependent manner." (PMID 34885121, 2021). "With this in mind, the importance of targeting receptors or the ligand as per GDNF and understand how to modulate the cancer microenvironment is clear." (PMID 33806299, 2021). "Abnormally high expression of GDNF is closely related to the initiation and development of malignant tumors." (PMID 32183903, 2020). "Multiple studies have reported the importance of mAbs in cancer; for example, an anti-mouse transferrin antibody fused with the GDNF (cTfRmAb-GDNF) can be delivered to the brain in vivo." (PMID 32957732, 2020). "Perineural invasion of some cancers is induced by GDNF, and in vivo models of perineural invasion of sciatic nerve are eliminated when Ret is silenced in the transplanted cancer cells." (PMID 32767110, 2020). "Either of downregulated APE1 or GFRα1 expression using small interference RNA (siRNA) inhibited GDNF-induced cancer cell proliferation." (PMID 32438692, 2020). "The neurotrophic factor receptor ‘REarranged during Transfection’ (Ret) and its major ligand, Glial cell line-Derived Neurotrophic Factor (GDNF), have established roles in axon growth, enteric nervous system and kidney development, and cancer progression." (PMID 31476133, 2019). "GDNF is secreted by nerves and its activity can enhance both cancer cells aggressiveness and neural invasiveness." (PMID 31248001, 2019). "Consistent with this notion, a recent study found that peripheral nerves secrete both GDNF and GFRa1, which attracts perineural invasion of heterogeneous cancer cells, some of which expresses Ret and Gfras, while some express only Ret." (PMID 25838128, 2015). "While it is attractive to consider specific therapeutics directed toward inhibiting the effects of GDNF in the context of standard cancer therapeutics, the DDSP is comprised of additional factors that have the potential to promote resistance phenotypes." (PMID 25575823, 2015). "High glucose caused the demyelinization and axonal degeneration of nerves, which facilitate cancer cell invasion into nerves and enhanced interactions between nerve and cancer cells by increasing the expression of cytokines such as GDNF." (PMID 24864247, 2014). "For example, based merely on miRNA regulation, we expected the expression level of GDNF should be upregulated, but some other factors have already been shown to involve in regulation of GDNF expression in cancers." (PMID 24564330, 2013). "Our group recently demonstrated that nerve secretion of glial-derived growth factor (GDNF) activates RET-receptor mediated cancer cell chemotaxis, guiding directional cell migration towards and along nerves." (PMID 22768171, 2012). "We found that the addition of anti-GDNF antibodies reduced the area of PNI by cancer cells as compared with controls treated with goat IgG." (PMID 22768171, 2012).